INS (insulin)
Diseases named in the same sentence as INS in open-access papers (continued):
Sharing a sentence is not in itself a finding about the gene and the disease.
Insulin resistance (continued). "Increased concentrations of fasting glucose and insulin, as well as increased values of homeostatic model assessment for insulin resistance (HOMA-IR), were found in the group of women with PCOS compared to the control group." (PMID 39201400, 2024). "This index is a much more accurate reflection of beta-cell function in the presence of prevailing insulin resistance than assessing insulin secretion alone." (PMID 38550917, 2024). "Accordingly, these mice showed hyperglycemia possibly resulting from an age-related insulin resistance, as ApN’s insulin-sensitizing effects were hindered." (PMID 39334732, 2024). "Studies of the brains of rat models of PD have revealed significantly decreased insulin levels and insulin resistance." (PMID 38818523, 2024). "Insulin resistance, the state of reduced responsiveness of target tissues to normal circulating insulin, is regarded as the central feature of T2DM and metabolic syndrome." (PMID 38225901, 2024). "The HOMA represents insulin resistance with the relationship between fasting glucose and insulin concentrations." (PMID 38536791, 2024). "The estimated likelihood of children with obesity developing insulin resistance is 38.7%, and the accumulation of visceral fat in their bodies independently contributes to insulin sensitivity." (PMID 40302954, 2024). "Insulin resistance is defined as an attenuated response to insulin leading to decreased insulin-stimulated glucose transport and metabolism in adipose tissue and skeletal muscle, as well as impaired suppression of endogenous glucose production in the liver." (PMID 38651416, 2024). "Insulin resistance (IR) is a condition characterized by the diminished ability of insulin to elicit its normal physiological effects in its target tissues, primarily muscle, adipose, and liver." (PMID 39741881, 2024). "Obesity is characterized by the accumulation of T cells in insulin-sensitive tissues, including the visceral adipose tissue (VAT), that can interfere with the insulin signaling pathway eventually leading to insulin resistance (IR) and type 2 diabetes." (PMID 38380252, 2024). "Inflammation also affects insulin sensitivity, and abundant evidence suggests that inflammation is directly related to insulin resistance." (PMID 39539361, 2024). "Chronic ingestion of polysorbate 80 in mice resulted in elevated plasma insulin levels and increased insulin resistance." (PMID 38892712, 2024). "In this situation, the main insulin-sensitive metabolic organs, such as the adipose tissue or the skeletal muscle, uptake glucose less efficiently, which leads to a whole status of insulin resistance, as with aging." (PMID 39456743, 2024). "This persistent inflammatory state not only disrupts insulin signaling but also contributes to systemic metabolic dysfunction, highlighting the intricate and multifaceted role of cytokines in insulin resistance." (PMID 39659426, 2024). "In the CAIDE study, which is a Finnish longitudinal study conducted over 7 years in older adults, insulin and insulin resistance (HOMA-IR) were predictors of global cognitive functioning." (PMID 39518747, 2024). "Chronic hyperinsulinemia and insulin resistance eventually lead to hypertension, reduced insulin secretion, and hyperglycemia." (PMID 39204141, 2024). "Insulin resistance has been shown to promote proliferation of fibroblasts and keratinocytes by insulin, insulin-like growth factor receptor-1 (IGFR1), and fibroblast and epidermal growth factors, resulting in the development of acanthosis nigricans." (PMID 38398863, 2024). "Insulin resistance influences the development of cognitive dysfunction due to hyperinsulinemia and impaired insulin signaling." (PMID 38397072, 2024). "Fructose metabolism, being insulin-independent, contributes to insulin resistance, elevated fasting glucose, insulin levels, and very low-density lipoprotein (VLDL) production." (PMID 38397356, 2024).
Insulin resistance (continued). "Previous studies have identified genetic biomarkers associated with GDM, illustrating its multifactorial nature involving hormonal changes, insulin resistance, and inadequate insulin secretion." (PMID 39355538, 2024). "Insulin resistance is a decrease in the sensitivity of insulin target tissues to insulin and the inability of normal levels of insulin to mediate appropriate levels of glucose-lowering action." (PMID 39906040, 2024). "SCFAs regulate pancreatic insulin secretion, prevent insulin resistance, and increase insulin sensitivity." (PMID 38998662, 2024). "In the prediabetic stage, pancreatic β-cells increase their insulin secretion to offset insulin resistance and regulate blood glucose levels." (PMID 39165284, 2024). "The pathogenesis of T2DM involves factors such as insulin resistance, impaired insulin secretion, increased hepatic glucose production, a sedentary lifestyle, and excessive calorie intake leading to obesity." (PMID 39767130, 2024). "SREBP1c, one of the transcription factors of SREBF1, exerts a pivotal role in insulin resistance and insulin signaling pathways." (PMID 39130628, 2024). "Homeostatic Model Assessment for Insulin Resistance (HOMA-IR) based on fasting insulin and glucose levels is an established measurement of insulin resistance." (PMID 39273678, 2024). "Following intervention, CHP mice showed improved body weight loss, enhanced glycaemic control, and alleviated symptoms of impaired insulin secretion and insulin resistance." (PMID 39063287, 2024). "Insulin resistance refers to the diminished ability of cells to respond to insulin, a hormone that regulates glucose uptake and metabolism." (PMID 39519193, 2024). "Severe insulin resistance is defined “as a severely diminished response to insulin’s biological effects and is characterized by substantial hyperinsulinemia and impaired response to endogenous and exogenous insulin”." (PMID 38397072, 2024). "These miRNAs and their target genes are significantly involved in metabolic pathways including insulin signaling, insulin resistance,f and PI3K-Akt signaling (padj <0.05)." (PMID 39037913, 2024). "Insulin resistance, also known as decreased insulin sensitivity, is defined as reduced ability of insulin to activate insulin signaling pathways, resulting in increased fasting serum glucose and other abnormalities in glucose and fat metabolism." (PMID 39119463, 2024). "In obese and diabetic patients, BBR combined with silymarin reduced fasting blood glucose and insulin, the insulin resistance index, HDL and LDL, triglycerides, uric acid, BMI, and the WHR." (PMID 39064727, 2024). "Insulin resistance impacts systemic metabolism and the brain directly by interfering with the brain’s insulin pathway." (PMID 39640295, 2024). "HF diet feeding in mice induced cardiac insulin resistance as shown by decreased glucose uptake in the heart during an hyperinsulinaemic-euglycaemic clamp (insulin clamp)." (PMID 38908792, 2024). "In the present study, UroA significantly enhanced GU by L6 myotubes in the insulin absence and oral administration of UroA to KK-Ay/Ta mice, a mouse model of T2D exhibiting insulin resistance, and suppressed blood glucose elevation in IPGTT." (PMID 38392186, 2024). "Glucocorticoids decrease the hepatic and systemic sensitivity to insulin and induce insulin resistance." (PMID 39439887, 2024). "In contrast to the more prevalent type 2 DM classically associated with the development of insulin resistance, T1DM is typically characterized by immune-mediated destruction of insulin-producing pancreatic β cells." (PMID 37902457, 2024). "Chronic lipid overload and high glucose levels disrupt astrocyte function, leading to insulin resistance characterized by impaired insulin signaling, reduced glycogen synthesis, and altered gene expression." (PMID 39830199, 2024).
Insulin resistance (continued). "In early-onset T2DM, β-cell failure is the end pathophysiological stage, preceded by insulin hypersecretion which initially compensates for the increased insulin resistance mainly on the grounds of obesity, ectopic adiposity, puberty, and inflammation." (PMID 38472622, 2024). "Animal studies have consistently shown that fructose affects plasma insulin levels and insulin resistance differently in males and females." (PMID 38999914, 2024). "For example, it has been demonstrated in animal models that insulin resistance promotes BP elevation by impairing synthesis of nitric oxide, while elevated BP impairs glucose intake by altering the delivery of insulin and glucose to skeletal muscle cells." (PMID 39217344, 2024). "Insulin resistance (IR) is a state of declined sensitivity of insulin receptors within the body, leading to a diminished hypoglycemic effect of insulin." (PMID 39852511, 2024). "In the insulin resistance HepG2 cell model induced by high insulin, AME also increased the glucose consumption of cells that developed insulin resistance." (PMID 39624841, 2024). "The role of ROS in insulin sensitivity is complex, with a dual effect: promoting insulin sensitivity in the early stages of disease, and contributing to insulin resistance as hyperglycemia progresses." (PMID 38397797, 2024). "Currently, HOMA-IR serves as a reliable indicator of insulin resistance by providing an estimation based on fasting blood glucose and serum insulin concentration." (PMID 40302954, 2024). "Traditional tools such as the homeostatic model assessment for IR (HOMA-IR) and quantitative insulin sensitivity check index (QUICKI), which use fasting insulin levels to measure insulin resistance, face practical limitations and variability." (PMID 38711979, 2024). "are regarded as probiotics, and genus Clostridium is positively correlated with INS sensitivity, suggesting its function in reducing insulin resistance." (PMID 38999906, 2024). "Elevated fasting glucose and insulin levels in F1 offspring juveniles and adults.Insulin resistance and abnormal glucose tolerance were only evident in F1 adults." (PMID 38251002, 2024). "In a murine model, PGRN administration alters glucose tolerance and insulin sensitivity, favoring insulin resistance." (PMID 39698038, 2024). "For example, individuals with lower gut bacterial diversity tend to exhibit higher insulin resistance, while insulin sensitivity is relatively higher in germ-free or gut microbiota-deficient mouse models." (PMID 39501848, 2024). "β-cell function in vivo must be considered not only in relationship with insulin resistance, but also with insulin clearance." (PMID 38578954, 2024). "The findings suggest that 6-OHDA induces neurodegeneration via activation of TLR4 and GSK3β, indicating insulin resistance, and that insulin can improve these impairments." (PMID 39830652, 2024). "Postnatal L-leucine showed downregulation, positively associated with insulin resistance and IFN-γ, probably because leucine stimulates insulin release and promotes protein biosynthesis." (PMID 38371596, 2024). "Insulin resistance is an insufficient cellular response to insulin in insulin-dependent cells like adipocytes, cardiomyocytes, and skeletal muscle." (PMID 38953241, 2024). "Il1r1Hep−/− mice showed lower levels of fasting insulin, homeostasis model assessment of insulin resistance, and adipose tissue insulin resistance indices following HFD feeding, albeit with comparable levels of circulating nonester fatty acid." (PMID 39621069, 2024). "The hallmark of type 2 diabetes is persistent hyperglycaemia resulting from a combination of peripheral insulin resistance and inappropriate secretion of insulin and glucagon from the pancreas." (PMID 38216792, 2024). "Insulin resistance can attenuate cellular insulin responsiveness, interfere with protein synthesis and degradation, and amplify nutritional risk." (PMID 38761298, 2024).
Insulin resistance (continued). "Impaired glucose tolerance (IGT), along with impaired fasting glucose (IFG), are documented to contribute to moderate insulin resistance in insulin-dependent tissues." (PMID 38612885, 2024). "The patients with impaired glucose tolerance, who had both lower insulin resistance and lower blood glucose levels, showed increased insulin secretion, this possibly pointing to better beta cell function." (PMID 38457064, 2024). "Insulin resistance, the impaired biological response of target tissues to insulin stimulation, is considered a central or pivotal pathogenic component of T2DM and metabolic syndrome." (PMID 38201980, 2024). "Insulin resistance also plays a significant role in the development of polycystic ovary syndrome, where high insulin levels lead to excessive androgen production." (PMID 39797110, 2024). "This disruption in insulin secretion results in an inability to facilitate glucose uptake and utilization, leading to the development of insulin resistance (IR)." (PMID 38633528, 2024). "Peripherally, asprosin induces hepatic glucose production and directly affects insulin signaling, leading to insulin resistance, inflammation, and endoplasmic reticulum stress, leading to lipid metabolism disorders and the onset of obesity." (PMID 39610397, 2024). "Remarkably, diminished insulin sensitivity at the level of the central nervous system, termed brain insulin resistance, constitutes a joint pathological feature of metabolic and cognitive dysfunction." (PMID 38843768, 2024). "Oxidative stress also impairs insulin signaling, exacerbates insulin resistance, and further promotes fat accumulation and liver inflammation." (PMID 38540163, 2024). "Vanadium compounds are known to exert insulin-enhancing activity, normalize elevated blood glucose levels in diabetic subjects, and show significant activity in models of insulin resistance (IR)." (PMID 38931427, 2024). "Lack of Adgrl1 in the VMH in mice caused fasting hyperinsulinaemia, enhanced glucose-stimulated insulin secretion and insulin resistance." (PMID 37712955, 2024). "T2DM is a metabolic disease caused by a failure in glycaemic control, mainly due to either insulin resistance or defective insulin secretion in a person’s body by pancreatic beta-cells." (PMID 38274329, 2024). "As previously revealed in animal experiments, ozone exposure in rats induces oxidative stress, endoplasmic reticulum stress and skeletal muscle insulin signal disruption, which in turn contribute to insulin resistance." (PMID 38091674, 2024). "Ceramide activates PP2A, reducing the activity of Akt, damaging the insulin signaling pathway, and inducing peripheral insulin resistance." (PMID 38379904, 2024). "In both mouse models, we observed T2D phenotypes, including hyperglycemia and insulin resistance, as detected by glucose tolerance tests and insulin tolerance tests." (PMID 39659577, 2024). "To examine the cellular mechanisms via which glucotoxicity induced insulin resistance, we examined in vivo glucose transport and whole-body insulin sensitivity in diabetic rats." (PMID 38426504, 2024). "A high-fat diet promotes insulin resistance in adipose tissue, which leads to hyperglycemia and lipotoxicity due to excess of lipolysis, as insulin plays a crucial role in glucose uptake and inhibition of lipolysis in adipose tissue." (PMID 38660995, 2024). "Using the HOMA-IR index, this study revealed the insulin resistance resulting from broilers exposed to an extended duration of light, which suggests the reduced abilities of insulin-mediated glucose metabolism in broilers." (PMID 39457933, 2024). "Compared with normal rats, model rats were kept with 4 weeks of HFD and injected with 4 weeks of LET (1 mg/kg/day), result in significant increases in fasting blood glucose (FBG), serum insulin, and homeostatic model assessment-insulin resistance (HOME-IR)." (PMID 39376609, 2024).
Insulin resistance (continued). "High glucose concentration induced insulin resistance, as shown by decreased insulin induced tyrosine phosphorylation of insulin receptor substrate-1 (lane 4) when compared to normal glucose (lane 2)." (PMID 39119463, 2024). "Insulin resistance, characterized by elevated insulin levels and diminished cellular responsiveness to insulin, is a pivotal component in various metabolic disorders." (PMID 39015535, 2024). "Regarding glucose metabolism, fasting glucose and 2 h glucose improved significantly in both groups, but fasting insulin and homeostatic model assessment of insulin resistance (HOMA-IR) only improved significantly in the subgroup with supra-median levels." (PMID 38928106, 2024). "A cross-sectional study conducted on patients diagnosed with diabetes mellitus type II showed that artificial sweeteners increased insulin resistance and that the duration of usage of artificial sweeteners exhibited a direct impact on insulin resistance." (PMID 38921683, 2024). "For example, impaired activation of the PI3K pathway in the case of insulin resistance reduces the antiatherogenic effects of insulin." (PMID 38846018, 2024). "Insulin resistance (IR), also referred to as impaired insulin sensitivity, arises when cells in the muscles, fat deposits, and liver exhibit a lack of insulin response." (PMID 39595541, 2024). "Insulin resistance represents the main pathogenic driver for T2DM and is characterized as a low response of insulin-targeting tissues to normal levels of insulin." (PMID 39768947, 2024). "Its pathophysiology is characterized by insulin dysregulation, leading to insulin resistance and pancreatic β-cell dysfunction, which primarily affects the liver, muscles, and adipose tissue." (PMID 39452068, 2024). "By inhibiting JNK1, the insulin signaling pathway was able to reduce insulin resistance and improve glucose metabolism." (PMID 39596859, 2024). "In T2DM, chronic hyperglycemia and insulin resistance are linked to increased BACE-1 levels and activity, as insulin signaling typically regulates BACE-1." (PMID 39766390, 2024). "The adipose tissue insulin resistance index (Adipo-IR index) is calculated as the product of the fasting insulin and free fatty acid (FFA) concentration and is useful in large-scale clinical practice." (PMID 39175570, 2024). "Firstly, ATP inhibits glucose metabolism through allosteric inhibition of enzymes in the glycolysis pathway, which downregulates glycolysis in the insulin-induced glucose metabolism pathway, contributing to insulin resistance." (PMID 39873003, 2024). "Blood pressure is higher in patients with insulin resistance than in those with normal insulin levels." (PMID 39768947, 2024). "In our study, probably due to changes in adiposity, decreasing lipolysis in adipocytes can bring insulin resistance, while increasing lipolysis can improve insulin sensitivity." (PMID 38167864, 2024). "Vitamin D has additional receptors in adipocytes, muscle, and hepatocytes reducing insulin resistance by enhancing insulin receptor expression and insulin responsiveness for glucose transport, and regulating calcium metabolism." (PMID 38459212, 2024). "When insulin resistance occurs, insulin cannot act on skeletal muscle cells and glucose in the blood is not taken up by the muscle cells." (PMID 38474229, 2024). "Glucagon contributes to systemic insulin resistance by antagonizing insulin action in multiple tissues, including the liver, adipose tissue, and skeletal muscle." (PMID 39873003, 2024). "In primary proximal tubule cells, insulin resistance has been found to impair the inhibitory role of insulin on cAMP-mediated processes related to glucose metabolism, and it makes sense that this would extend to loss of inhibition of lipolysis as well." (PMID 38280449, 2024).